APOE (apolipoprotein E)
Diseases named in the same sentence as APOE in open-access papers (continued):
Sharing a sentence is not in itself a finding about the gene and the disease.
Hypercholesterolemia (495 papers, 2008 to 2026). An increased concentration of cholesterol in the blood. "One plausible mechanism is that APOE ε4 carriers exhibit heightened inflammatory responses to environmental or pathological stressors, including comorbidities such as hypercholesterolemia and ischemic heart disease, to which they are predisposed." (PMID 40665049, 2025). "ApoE-deficient mice develop severe hypercholesterolaemia and atherosclerotic lesions resembling human lesions." (PMID 40026711, 2025). "ApoE deficiency in humans is related to a reduced breakdown of atherogenic lipoproteins, promoting hypercholesterolemia and AS development." (PMID 38628207, 2024). "For instance, single nucleotide polymorphism (SNPs) in apolipoprotein E (APOE) can cause hypercholesterolemia with strong associations for development of coronary artery disease." (PMID 38247511, 2024). "To investigate the role of ASGR1 deficiency on plasma lipid profile during hypercholesterolemia, we fed ApoE−/− and ApoE−/−/ ASGR1−/− mice with western-type diet (WTD) for 16 weeks." (PMID 39616371, 2024). "Lastly, APOE, encoding apolipoprotein E and playing a key role in lipid metabolism, has SNPs rs7412 for Pure hypercholesterolaemia and rs429358 for IHD." (PMID 38144368, 2023). "APOE was previously linked to hypercholesterolemia and hypertriglyceridemia, both of which are correlated with psoriasis." (PMID 37569685, 2023). "Patients with familial hypercholesterolemia (FH) have increased levels of HDL-associated apoE which is believed to play a role in aberrant HDL catabolism." (PMID 36626966, 2023). "Hyperuricemia, hypercholesterolemia, and ApoE gene polymorphism are all important risk factors, affecting left ventricular remodeling." (PMID 36620636, 2022). "Switching Western-type-diet-fed APOE KO mice with established atherosclerotic lesions back to a chow diet was associated with a reduction in the hypercholesterolemia extent and an increase in the absolute lesion size and plaque collagen-to-macrophage ratio." (PMID 36139044, 2022). "Some alleles (APOE ε4) of the gene for apolipoprotein E result in the development of hypercholesterolemia and have been found in 40% of AD patients." (PMID 36232867, 2022). "Apolipoprotein E (ApoE) regulates lipid homeostasis and cholesterol metabolism, and ApoE deficiency leads to hypercholesterolemia." (PMID 35735797, 2022). "Altogether, these results suggest that the p.Leu167del APOE variant was associated with a monogenic form of hypercholesterolemia, increased LDL-C levels, and reduced TG levels compared to other APOE variants." (PMID 35628605, 2022). "Epidemiological data confirmed that hypercholesterolemia and hyperlipoproteinemia, mainly ApoE, in midlife increase the risk for the development of late-onset AD." (PMID 36291224, 2022). "We first determined the effects of AID deficiency on diet-induced hypercholesterolemia in the ApoE-/- background." (PMID 34305930, 2021). "Hypercholesterolemia associated with the apolipoprotein E (APOE) ε4 allele, and overweight have been reported to be more prevalent in SC subjects." (PMID 34684338, 2021). "There have been limited studies regarding the association between the APOE gene and hypercholesterolemia in the Hispanic population; therefore, our aim for this study is to examine the APOE gene’s associations with cholesterol level and its related phenotypes." (PMID 34828374, 2021). "Taken together, these results indicate that spontaneous hypercholesterolemia in mice deficient for ApoE exerts minimal influence on development and progression of PPE-induced experimental AAAs." (PMID 34680067, 2021).
Hypercholesterolemia (continued). "In the study by Yamamoto, the expression of ApoE Sendai resulted in insufficient normalization of hypercholesterolemia in ApoE-deficient mice and induced high plasma levels of triglyceride." (PMID 33663537, 2021). "The results of the current study demonstrate that the APOE e4 allele carries a high risk for cholesterol-related traits, including hypercholesterolemia, in the Hispanic population." (PMID 34828374, 2021). "In our study, the hypercholesterolemia associated APOE ε4 allele suggests that individuals carrying the APOE ε4 allele(s) are at an increased risk of hypercholesterolemia development in the Hispanic population." (PMID 34828374, 2021). "A total of 211 (25.9%) participants with hypercholesterolemia carried at least one copy of the APOE ε4 allele." (PMID 34828374, 2021). "A previous study of 425 Hispanic participants (193 with and 232 without cerebral amyloid angiopathy) reported a higher prevalence of stroke and hypercholesterolemia in non-APOE ε4 allele carriers." (PMID 34828374, 2021). "This is the first report of significant findings of the APOE ε4 allele’s association with hypercholesterolemia in the Hispanic population." (PMID 34828374, 2021). "Collectively, these findings suggest that ApoE−/− mediated hypercholesterolemia was exaggerated by the null mutation of Dscr-1 due to the impairment of cholesterol clearance." (PMID 33895138, 2021). "Apolipoprotein E (APOE) has been studied to explore the effects of hypercholesterolemia on the progression of OA by constructing ApoE-deficient mice and dietary hypercholesterolemia rats." (PMID 34949204, 2021). "Chi-square test revealed a significant association between APOE ε4 allele and hypercholesterolemia (p = 1.17 × 10−4)." (PMID 34828374, 2021). "Accordingly, ApoE-deficient mice (ApoE−/−), which are characterized by hypercholesterolemia and hypertriglyceremia (own unpublished data), showed a significant impairment of cognitive function potentially related to AD pathology such as tauopathy." (PMID 33029684, 2020). "As a consequence, deficiency in ApoE rapidly induces dyslipidaemia and hypercholesterolemia in ApoE–/– mice, leading to hepatic steatosis and liver injury." (PMID 33291840, 2020). "We replicate this finding, showing an additional risk of homozygous APOE ε4 status and hypercholesterolemia in a larger cohort with complete data." (PMID 32971464, 2020). "The present results demonstrated that XO inhibition significantly reduced hypercholesterolemia-associated kidney inflammation and fibrosis in uninephrectomized ApoE KO mice." (PMID 33050202, 2020). "In uninephrectomized ApoE KO mice, the HC diet increased cholesterol accumulation, oxidative stress, XO activity, and kidney damage, while topiroxostat attenuated the hypercholesterolemia-associated renal dysfunction." (PMID 33050202, 2020). "Other identified genes that were less frequently detected in familial hypercholesterolemia encode apolipoprotein E (APOE) and the signal-transducing adaptor family member 1 (STAP1)." (PMID 32528276, 2020). "Mutations in the APOE gene are associated with familial hypercholesterolemia associated with premature cardiovascular disease." (PMID 32366041, 2020). "Lactobacillus mucosae DPC 6426 has previously demonstrated potentially cardio-protective properties, in the form of dyslipidaemia and hypercholesterolemia correction in an apolipoprotein-E deficient mouse model." (PMID 30736731, 2019). "ApoE plays a major physiological role in lipoprotein metabolism; ApoE deficiency is associated with hypercholesterolemia." (PMID 31695628, 2019).
Hypercholesterolemia (continued). "In summary, hypercholesterolemia in an in vivo APOE*3-Leiden mouse model causes a pre-ischemic peripheral monocytosis and impaired systolic and diastolic cardiac function eight weeks after myocardial ischemia-reperfusion injury." (PMID 31199833, 2019). "We used apolipoprotein E-deficient mice (ApoE-/-) for our studies, because they develop spontaneous severe hypercholesterolemia and atherosclerotic lesions in various blood vessels similar to those found in humans." (PMID 31781340, 2019). "An animal model pointed out that female offspring (APOE +/-) presented a high susceptibility to form neointima after exposition to maternal hypercholesterolemia (APOE-/-)." (PMID 31547615, 2019). "Apolipoprotein E (APOE) is a key component in cholesterol metabolism and Apoe-deficient mice cause hypercholesterolemia." (PMID 31001203, 2019). "It had generally been assumed that systemic hypercholesterolemia is the major proatherogenic factor in ApoE-deficient mice." (PMID 30354237, 2018). "It is reported that upregulation of vascular inflammation is triggered by excessive oxidative activity of circulating white blood cells, induced by hypercholesterolemia or liver dysfunction in apoE-deficient mice." (PMID 29584779, 2018). "APOE-deficient mice are characterized by severe hypercholesterolemia due to a virtually completely blocked LDL-receptor mediated lipoprotein remnant clearance." (PMID 30409998, 2018). "APOE deficiency in humans is a rare phenomenon but has a broad range of phenotypes spanning from mild hypercholesterolaemia to severe xanthomatosis, hyperlipoproteinaemia and development of premature atherosclerosis." (PMID 28688452, 2017). "Apolipoprotein E deficient mice (ApoE−/− or E0 mice) are widely used as atherosclerotic animal model, since they develop severe hypercholesterolemia on a regular chow diet." (PMID 29226146, 2017). "Assessment of arthritis development in ApoE-deficient mice using the CIA model has led to conflicting reports on the consequences of hypercholesterolemia on promoting arthritis." (PMID 28724439, 2017). "Heterozygous mutations in LDL Receptor, Apolipoprotein B, PCSK9, and Apolipoprotein E are linked to hypercholesterolemia." (PMID 29230236, 2017). "ApoE deficiency in mice has been also shown to result in spontanenous atherosclerotic plaque formation also seen in humans with severe hypercholesterolaemia." (PMID 28688452, 2017). "P.Leu167del mutation in APOE gene was recently connected with Familial Hypercholesterolemia, a condition associated with premature cardiovascular disease." (PMID 29204218, 2017). "To assess the role of the sympathetic nervous system and its modulation by RDN, we used a novel, normotensive ApoE-deficient rat model of hypercholesterolemia with a hitherto uncharacterized cardiovascular phenotype." (PMID 27277003, 2016). "Altogether, these results suggest that ApoE deficiency and perhaps the associated hypercholesterolemia are critical for colon homoeostasis." (PMID 27538678, 2016). "Apolipoprotein E-deficient (ApoE−/−) rodents spontaneously develop severe hypercholesterolemia and increased aortic stiffness, both accepted risk factors for cardiovascular morbidity and mortality in humans." (PMID 27277003, 2016). "APOE-e4 associated with a higher likelihood of hypercholesterolemia and overall illness index scores (ps < .05)." (PMID 27486898, 2016). "Overall, our study calls for caution about the effects of ApoE deficiency not only in lipid metabolism and the subsequent risk for hypercholesterolemia but also as a major risk factor for diseases of the colon." (PMID 27538678, 2016).
Hypercholesterolemia (continued). "Diet-induced hypercholesterolemia in ApoE-deficient mice has been shown to induce monocytosis associated mainly with a shift toward an increased frequency of the Gr1high subset compared with Gr1low fraction." (PMID 26344769, 2015). "While the Apoe−/− mice is a standard model for hypercholesterolemia and apoE has been implicated in body weight control, genetic evidence for tissue specific actions of apoE is scarce." (PMID 26695075, 2015). "This can be explained by a constitutive pro-inflammatory state that has been shown with ApoE deficiency in association with hypercholesterolemia." (PMID 24586873, 2014). "Hypercholesterolemia caused by ApoE gene deletion leads to upregulation of AT1 receptors, which would be expected to facilitate inflammation and oxidative stress through the activation of matrix metalloproteinases and production of reactive oxygen species." (PMID 25398022, 2014). "ApoE -/- mice (like individuals with ApoE linked familial hypercholesterolemia) develop xanthomas — connective tissue deposits of lipid containing high levels of cholesterol and LDL and increased numbers of macrophages." (PMID 25502628, 2014). "We first evaluated the impact of prolonged hypercholesterolemia on Cx36 expression in vivo using the hypercholesterolemic, pro-atherogenic ApoE deficient mouse (ApoE−/−) and observed that the Cx36 levels were decreased in ApoE−/− compared to WT mice." (PMID 23383107, 2013). "Apolipoprotein E-deficient mice (apoE−/−) develop spontaneous hypercholesterolemia in a few weeks and also display morphological and ultrastructural alterations in RPE similar to those in human AMD." (PMID 23738034, 2013). "This study is the first to demonstrate the impact of hypercholesterolemia associated with aging process on production of ROS, DNA damage and apoptosis in bone marrow mononuclear cells in apoE−/− animals." (PMID 23385237, 2013). "And the apoE-/- mice are gene-deficient animal model, in which targeted deletion of apoE gene leads to severe hypercholesterolemia and spontaneous." (PMID 22762542, 2012). "The ApoE gene (19q13.2) has three major isoforms encoded by ε2, ε3 and ε4 alleles with the ε4 allele associated with hypercholesterolemia and the ε2 allele with the opposite effect." (PMID 23098561, 2012). "Among the genetically engineered models, the apoE-deficient (apoE-/-) mouse is considered to be one of the most relevant models because it develops spontaneous hypercholesterolemia and arterial lesions similar to those observed in humans." (PMID 22330242, 2012). "The importance of studying a murine model that lacks the functional gene encoding the apolipoprotein E is that it develops spontaneous hypercholesterolemia and atherosclerotic lesions similar to those found in human beings." (PMID 22117541, 2011). "In our population, APOE ε2 allele confers protection against hypercholesterolemia and a less atherogenic lipid profile." (PMID 22074026, 2011). "Our results showed differences in genotype and allele frequencies between normolipidemic and hypercholesterolemic groups, suggesting that APOE ε2 allele confers protection against hypercholesterolemia." (PMID 22074026, 2011). "The murine model that lacks the gene encoding apolipoprotein E (ApoE) and spontaneously develops hypercholesterolemia and atherosclerotic lesions similar to those found in human beings has greatly contributed to the understanding of this disease." (PMID 20482882, 2010). "Actually, our finding was confirmed by results of other studies who found positive correlation between APOE polymorphism and hypercholesterolemia." (PMID 19804633, 2009). "Further, association was also established between ESR1 and APOE genetic polymorphisms and hypercholesterolemia." (PMID 19804633, 2009). "A study found that DEHP-exposed, apolipoprotein-E-deficient mice may have hypercholesterolemia and fatty livers." (PMID 38640138, 2024).
Hypercholesterolemia (continued). "The SKH-hr2+ApoE mice demonstrated an increase in the sebum levels, which could be associated with the strain genetic hypercholesterolemia." (PMID 39456640, 2024). "Specifically, in an ApoE-deficient mouse model, which exhibits severe hypercholesterolemia and atherogenic lesions similar to those found in humans, taurine supplementation inhibited the development of atherosclerotic lesions and showed protective potential against cardiovascular disease." (PMID 39199235, 2024). "Specifically, Miles demonstrated that AT mice maintain normal insulin sensitivity but experience transient hyperglycemia during an oral glucose tolerance test; Wu found that heterozygous mutation of the ataxia-telangiectasia mutated gene exacerbates hypercholesterolemia in apoE-deficient mice." (PMID 39326070, 2024). "Midlife hypercholesterolemia is associated with heightened AD risk, suggesting that APOE’s involvement in lipid metabolism may contribute to AD risk." (PMID 38574442, 2024). "Therefore, its absence (ApoE-/-) caused hypercholesterolemia which led to an accumulation of leukocytes and plaque formation." (PMID 36851139, 2023). "PAVs in the hypercholesterolemia-associated APOE gene were associated with apoB (p=3.5×10−4), total HDLC (p=8.0×10−4), and total cholesterol and cholesterol esters in LDL particles, with large negative effects observed for the previously reported rare p.Glu57Lys (rs201672011) variant." (PMID 36419110, 2022). "In this model, an Azlet osmotic pump will be implanted subcutaneously in mice that are susceptible to hypercholesterolemia (e.g., ApoE-/-), providing subcutaneous infusion of angiotensin II at a dose of 500 or 1,000 ng/kg/min for varying durations, ranging from 14 to 28 days." (PMID 36035911, 2022). "Another experimental study convincingly associates high fat diet-induced hypercholesterolemia in aged ApoE-/- mice not only with elevated plasma levels of IL6, TNF-α, and interferon (IFN)-γ but also higher transcript levels of pro-inflammatory chemokine MCP-1 in brain tissue of these mice." (PMID 34349106, 2021). "Chronic hypercholesterolemia that was accompanied by moderate blood pressure elevations associated with apparent immune system activation characterized by increases in circulating pro-inflammatory Ly6Chi monocytes in ApoE-/- mice." (PMID 34349106, 2021). "Strikingly enough, while peripheral ApoE4 is a major risk factor for hypercholesterolemia, it remains largely unknown how ApoE isoforms affect cholesterol metabolism in the brain." (PMID 34248607, 2021). "Deletion of the ApoE gene caused an inability in clearance of circulatory lipid and even a boost in the sensitivity to a dietary cholesterol, making the mice suffer a severe hypercholesterolemia." (PMID 34836239, 2021). "Furthermore, in 153 other hypercholesterolemia probands, three APOE variants were detected, of which the p.(Leu167del) variant was found to segregate within a family with hypercholesterolemia." (PMID 34440342, 2021). "In this context, it is described that hypometabolism of glucose per se is associated with cholesterol-related AD progression, which may be linked to ApoE deficiency-induced hypercholesterolemia and impaired glucose metabolism." (PMID 33029684, 2020). "APOE ε4 is the gene variant that is associated with increased risk of late-onset sporadic AD and may potentially predispose carriers to hypercholesterolemia." (PMID 32300296, 2020).